SPEF1 (sperm flagellar and cilia associated 1)
Description:
Microtubule-associated protein involved in the stabilization of microtubules along the axis of migration during radial intercalation. Promotes the establishment and stabilization of an axis of microtubules required for the active migration of cells into the outer epithelium (By similarity). Microtubule-associated protein that promotes microtubule bundling and stabilizes microtubules against depolymerization in response to cold shock (By similarity). Essential for ciliary central apparatus formation which requires both its microtubule-binding and bundling activities and for ciliary localization of HYDIN and SPAG6 in ependymal cilia (By similarity). Binds actin in intestinal epithelial cells (IECs), essential for IECs survival and contributes to formation of filopodia and lamellipodia in migrating IECs. Regulates planar cell polarity signaling pathway and asymmetric microtubule accumulation in ciliated epithelia (By similarity).
Synonyms: C20orf28; DKFZP434I114; SPEF1A; CLAMP
Tractability: Antibody: UniProt places it where antibodies can reach, with high confidence; its Gene Ontology location is reachable by antibodies, with medium confidence.
Gene: Protein-coding gene on chromosome 20 (3,777,504 to 3,781,448, reverse strand). Ensembl gene ENSG00000101222.
Subcellular location: Cytoplasm; Cell projection, cilium, flagellum; Cytoplasm, cytoskeleton, cilium axoneme; Apical cell membrane; Basolateral cell membrane; Cytoplasm, cytoskeleton, stress fiber; Cell projection, microvillus; Cell projection, lamellipodium; Cell projection, filopodium
Gene Ontology:
Molecular function: actin binding; protein binding; microtubule binding; cytoskeletal protein binding
Biological process: filopodium assembly; lamellipodium assembly; axonemal central apparatus assembly; cell migration; cilium movement; microtubule bundle formation; negative regulation of microtubule depolymerization; regulation of cytoskeleton organization; regulation of Wnt signaling pathway, planar cell polarity pathway
Cellular component: apical plasma membrane; basolateral plasma membrane; cytoplasm; filopodium; lamellipodium; microtubule; microvillus; 9+2 motile cilium; axonemal central apparatus; axoneme; ciliary tip; cytoskeleton; motile cilium; plasma membrane bounded cell projection; stress fiber
Genetic constraint (gnomAD): Loss-of-function variants: 29 observed, 29.96 expected, observed/expected ratio (o/e) 0.97, 90% interval 0.72 to 1.32. The upper end of that interval is the gene's LOEUF score, 1.32, which puts it in group 5 of 6, group 1 being the genes least tolerant of losing a copy. Missense variants: 298 observed, 304.18 expected, observed/expected ratio (o/e) 0.98, 90% interval 0.89 to 1.08. Synonymous variants: 126 observed, 125.86 expected, observed/expected ratio (o/e) 1, 90% interval 0.87 to 1.16.
Homologues: Orthologues: chimpanzee SPEF1 (99% identical), macaque SPEF1 (96% identical), pig SPEF1 (92% identical), dog SPEF1 (91% identical), guinea pig SPEF1 (88% identical), mouse Spef1 (88% identical), rabbit SPEF1 (88% identical), tropical clawed frog spef1 (58% identical), zebrafish spef1 (43% identical), rat LOC103691261 (40% identical). Paralogues in human: SPATA4 (20% identical).
Diseases named in the same sentence as SPEF1 in open-access papers:
SPEF1 is named in the same sentence as 4 diseases in open-access papers, as found by Europe PMC text mining. Sharing a sentence is not in itself a finding about the gene and the disease. The quoted sentences say what the papers report.
ciliopathy (1 paper, 2025). A genetic disorder of the cellular cilia or the cilia anchoring structures, the basal bodies, or of ciliary function. "Given the critical involvement of Ccdc13 and Spef1 in motile cilia function, it would be of great interest to explore whether mutations in these genes contribute to ciliopathies." (PMID 40492112, 2025). "Furthermore, understanding how Ccdc13 and Spef1 interact with other ciliopathy-related proteins could reveal deeper insights into the molecular basis of motile cilia dysfunction, with significant implications for the development of targeted clinical therapies." (PMID 40492112, 2025).
cancer (2 papers, 2022 to 2025). A tumor composed of atypical neoplastic, often pleomorphic cells that invade other tissues. "This study investigated the expression of cancer-testis antigens SPEF1 and SPEF2 in BLCA using comprehensive bioinformatic analyses to assess their potential as biomarkers." (PMID 40747466, 2025). "The current study was the first of its kind to explore the potential clinical role of SPEF1 and SPEF2 in BLCA, building upon previous research that identified these proteins in other cancers and potentially premalignant lesions." (PMID 40747466, 2025).
SPEF1 also shares sentences with these, for which no sentence is quoted: tumor (2 papers); bladder cancer (1).